IL6R (interleukin 6 receptor)
Diseases named in the same sentence as IL6R in open-access papers (continued):
Sharing a sentence is not in itself a finding about the gene and the disease.
tumor (continued). "Notably, we observed that the intragenic hypermethylation of IL6R was generally associated with a poor prognosis in different tumors, thus highlighting the specific role of IL6R expression in tumor progression." (PMID 34576335, 2021). "High levels of pretreatment tumor IL-6R and serum IL-6 expression have been shown to correlate with a higher rate of tumor recurrence and reduced survival of HNSCC patients, which emphasizes the relevance of inhibiting this signaling pathway to mitigate the risk of recurrence in HNSCC." (PMID 34689150, 2021). "Moreover, IL6R predictive value for cancer patients’ overall survival was significant (p ≤ 0.05) in six tumor types, however displaying a different trend among these." (PMID 34576335, 2021). "Meanwhile, the gene IL6R expression showed a positive correlation with tumor‐infiltrating lymphocytes in HSIL, solidifying the activation of the JAK/STAT3 signaling pathway contributing to inflammation occurring in the very early stage and promoting the neoplasia." (PMID 33694292, 2021). "We hypothesized that targeting the cytokine to tumor tissue by utilizing peptides that could bind receptors upregulated in tumor cells, such as the interleukin-6 receptor (IL-6Rα), could help augment IL-27 bioactivity." (PMID 32046108, 2020). "In addition to fibroblast-derived IL-6, we verify that exogenous IL-6 induces CRC cell invasion via IL-6R, consistent with previous study that anti-IL-6R antibody suppresses angiogenesis and inhibits the interaction between tumor and stroma." (PMID 32855767, 2020). "Then, tumor-tropic BM-MSCs circulated to primary sites and triggered CD151+/CD38+ cells acquiring EMT-associated CSC properties through IL6R/pY705-STAT3 signaling to promote tumor initiation and were also attracted by and migrated towards the premetastatic niche." (PMID 33262462, 2020). "Although the involvement of the IL-6R/STAT3 signaling pathway in EOC has been explored with regard to tumor progression and chemoresistance, the use of antibodies (siltuximab and tocilizumab) targeting this signaling pathway has not generated clear clinical relevance." (PMID 31448054, 2019). "Similarly, mRNA expressions of IL-6R and myostatin were increased in the tumor control group, whereas they were significantly reduced in response to ajoene extract treatment (IL-6R, p = 0.042; myostatin, p < 0.001)." (PMID 31717643, 2019). "Additionally, a fresh portion of each tumor was used to generate single cells and immediately labeled with anti-IL-6R and -CD90 antibodies." (PMID 31014367, 2019). "Our preliminary simulations of the experimental system that includes human endothelial cells show that increased amplification, along with additional IL-6R engagement, can predict the faster tumor growth dynamics that are observed with that experimental approach." (PMID 29351275, 2018). "Simultaneously, significant decrease in the number of CD11b+Gr-1− e-MDSCs in primary tumor tissues was also observed in IL-6R Ab- and JSI-124-treated mice when compared with untreated controls (22.73 ± 2.39 vs. 21.70 ± 1.55 vs. 46.70 ± 3.70%, P = 0.0055, P = 0.0034)." (PMID 30083161, 2018). "Whether circHIPK3 can affect the tumor immune response by promoting IL-6R remains to be further explored." (PMID 29626935, 2018). "Inactivation of IL-6 or the IL-6Rα in mice reduces tumor formation in the CAC mouse model." (PMID 30591653, 2018). "We also used the model to predict tumor response to administration of the humanized IL-6R monoclonal antibody, tocilizumab (TCZ), and we found that as little as 1mg/kg of TCZ administered weekly for 7 weeks is sufficient to result in tumor reduction and a sustained deceleration of tumor growth." (PMID 29351275, 2018).
tumor (continued). "IHC staining for IL6R from in vivo tumours demonstrated either IL6R silencing or overexpression." (PMID 29258522, 2017). "In addition, IL6R overexpression significantly promoted intracranial tumour growth and decreased survival of tumour-bearing mice (median survival: 61 ± 5.4 days vs. 29 ± 2.1 days, respectively)." (PMID 29258522, 2017). "This supports the idea, that the tumor angiogenesis is inhibited by an IL-6R blockade." (PMID 28903416, 2017). "We postulate that tumor cells may acquire migratory phenotype through the IL-6/IL-6R/STAT3 axis, and potent chemokines, such as CXCL8, initiate the actual cellular movement to a specific direction." (PMID 29245982, 2017). "In addition, we observed an increase in IL-6Rα levels in tumour cells and soluble IL-6R serum levels as well as increased Stat3, IL-6Rα and IL-6 mRNA levels in Ptenpc−/− PCa compared with WT controls." (PMID 26198641, 2015). "Accordingly, miR-34a suppression, which is common in cancer cells, and consequent enhanced production of s-IL-6R could activate JAK/STAT signaling in stromal cells of the tumor microenvironment." (PMID 26091352, 2015). "IL-6 is known to affect tumor migration by binding to cell-surface IL-6R molecules." (PMID 24398980, 2014). "Due to being one of the most ubiquitously deregulated cytokines in cancer, IL-6 is shown to modulate growth and differentiation in several malignant tumor cells and its overexpression with its receptors (IL-6R and sIL-6R) has been found in a wide range of cancers." (PMID 24670367, 2014). "MDSCs from tumor-bearing mice generated more soluble IL-6Rα compared to 4T1 cells." (PMID 24021059, 2013). "Thus MDSCs that were expanded and recruited in the metastasizing tumor-bearing mice were already capable of soluble IL-6Rα production, even in the spleen, a site remote from the metastasizing cancer cells." (PMID 24021059, 2013). "Following the precise identification of tumour cell dependence for IL-6 (expression of IL-6 and its receptor IL-6R) in a panel of ten cell lines (of myeloma, leukemia or lymphoma origins), we determined their individual response to different doses of radiations and chemotherapeutic drugs." (PMID 19956602, 2009). "However, it is unclear whether the STAT3/miR-34a/IL-6R loop plays the same role in different tumor cells, which requires further research." (PMID 38172648, 2024). "IL-6/IL-6R inhibition may be an effective strategy to inhibit tumor progression and metastasis." (PMID 37208766, 2023). "Therefore, we hypothesized that IL-6/IL-6R might play a role in regulating tumor suppressor genes in GBMs cells through a common downstream molecular mechanism." (PMID 36106122, 2022). "Similarly, knockdown of IL6R in tumor cells suppressed both IL-6/JAK/STAT3 and TGFβ signaling, and suppressed EVsMMA-MRC5-induced EMT marker expression, drug resistance, and invasion and migration, suggesting that IL-6R activation functions upstream of TGFβ pathway signaling in this context." (PMID 36266345, 2022). "Furthermore, the direct fusion of an anti-IL-6R that blocks further downstream signalling by inhibiting the JAK/STAT pathway responsible for the promotion of tumour growth and metastasis could provide beneficial anti-tumour properties." (PMID 36439165, 2022). "Finally, our studies suggest that strategies as diverse as targeting tumor cell production of IL-6, IL6R shedding from muscle and other tissues, adipose lipolysis, or lipid uptake by muscle might each show benefit in PDAC." (PMID 33851955, 2021). "Therefore, we assessed if the combination of cytotoxic chemotherapy and IL-6R blockade might also promote tumor control in a preclinical model of PDAC subcutaneously injected into WT mice." (PMID 34711820, 2021). "Moreover, all CC tissues were IL-6R positive, especially in the tumor front (CC)." (PMID 31396215, 2019).
tumor (continued). "In addition, systematic administration of IL-6/IL-6R antagonist(s) with MCT-1 inhibitor(s) may promote immune cell infiltration to advance therapeutics against tumor heterogeneity and aggressiveness, with fewer adverse effect(s)." (PMID 30885232, 2019). "Finally, inhibition of IL-/IL-6R signalling hampered the tumour invasion and angiogenesis." (PMID 29695771, 2018). "As we observed similar total macrophage numbers in tumour tissues independent of genotype, we next asked whether IL-6Rα deficiency might alter specific macrophage subsets in CAC." (PMID 29695802, 2018). "Moreover, Ccl20 and Ccr6 increased in obese control tumours and were downregulated in non-tumour tissue and tumours of obese IL-6Rα-deficient mice." (PMID 29695802, 2018). "However, while IL-6 deficiency ameliorates DEN-induced HCC in lean and obese mice, inactivation of IL-6 receptor alpha (IL-6Rα) reduces DEN-induced tumor burden only in lean mice, suggesting a compensatory overlapping signaling cascade in obese IL-6Rα-deficient mice." (PMID 30224299, 2018). "However, depletion of IL-6R did not completely abrogate the malignancy promotion conferred by MGDAs, indicating that an unknown pathway distinct from the IL-6R/IL-6 signalling mediates the promotion of tumour malignancy by adipocytes." (PMID 28281525, 2017). "Compared with HCC tumor tissue, several EC proliferation and angiogenesis-related genes in peritumoral tissue were gradually up-regulated during seven weeks of tumor growth, including IL-6, IL-6R, and gp130, which was confirmed by RT-PCR (using mouse-specific primers), IHC staining and Western blot." (PMID 26525581, 2015). "Within the tumor microenvironment (TME), stromal cells and malignant clones secrete IL-6, which activates gp130/JAK/STAT3 cascades through IL-6 receptor (IL-6R) binding." (PMID 40733153, 2025). "Conversely, we identified that tumours with low ratios enrich inflammatory/ECM-disrupting genes, such as IL6R, VCAM1, and MMP13, which collectively drive immune suppression and metastasis, in accordance with a poor prognosis and increased invasiveness." (PMID 41007296, 2025). "Our results show that the levels of CD109, IL6Rα, pSTAT3 and NRF2 are markedly upregulated in tumor sections compared to normal tissue and CD109 levels correlate significantly with those of IL6Rα/pSTAT3/NRF2." (PMID 40317079, 2025). "The IL6/IL6R/gp130 complex activates signaling pathways via STAT3 and MAPK activation, which not only drive angiogenesis but also contribute to tumor progression." (PMID 40427188, 2025). "Other inflammatory mediators like tocilizumab (anti-IL-6R) and bevacizumab (anti-VEGF) are promising, with reports of significant tumor volume reduction after recurrences." (PMID 40433410, 2025). "Upon binding to the IL‐6 receptor (IL‐6R) on cell membranes, IL‐6 forms a complex with gp130 or IL‐6Rβ, triggering STAT3 activation and promoting tumor development." (PMID 40166646, 2025). "Several preclinical studies have shown significantly improved tumor control and survival with combination IL-6 blockade (anti-IL6 or anti-IL-6R) and ICI compared with ICI alone, which was postulated to be due to improved Th1/Th17 skewing." (PMID 39403935, 2024). "In the present study, by integrating scRNA-seq data with TCGA HNSCC dataset, we identified five enriched pathways, including IL6/IL6R and CCL2/CCR2 signaling, within NK cells and tumor cells in the HPV − HNSCC cohort compared to the HPV + counterpart." (PMID 38468260, 2024). "As high IL-6, s-IL-6Rα, and s-gp130 predicted survival among the HPV(−) tumor patients, activation of both the classical and trans intracellular pathways seem to be associated with both increased HNSCC-caused and general mortality." (PMID 38672565, 2024). "Simultaneously, SPP1 downregulated CD40LG, TNFSF15, TNFRSF13B, IL6R, KLRK1, and other immune stimulants, indicating that SPP1 played a role in the evasion of tumor immunity by controlling the immunosuppressive surroundings." (PMID 38329443, 2024).
tumor (continued). "IL-6R immunotherapy plus MCT-1 knockdown effectively decreased the immunosuppressive TME, better supporting the prevention of primary and secondary tumor spreading than monotherapy." (PMID 38505617, 2024). "IL6R and CCL2 exhibited elevated expression in NK cells in HPV − tumor tissues compared with HPV + tumor tissues." (PMID 38468260, 2024). "Targeted proteomics identified IL-6 and M-CSF as dominant drivers, and we show that IL-6R and CSF1R inhibition prevents tumor-induced CD14+ cDC2s." (PMID 38242119, 2024). "Our finding that simultaneous inhibition of IL-6R and CSF1R drastically reduces tumor-induced cDC2 to CD14+ DC conversion creates several therapeutic possibilities." (PMID 38242119, 2024). "Our study also provided evidence that the IL6/IL6R and CCL2/CCR2 signaling pathways within the TME exert a greater influence on the ability of HPV − tumor cells to evade immune attack by NK cells compared to HPV + tumors." (PMID 38468260, 2024). "The tumor slices from human CRC SW480 and HT-29 xenografts were subjected to assessment of the IL-6R signaling pathways, including phosphor-STAT3 and phosphor-Erk-1/-2 levels in the untreated and treated groups." (PMID 38256960, 2024). "Immunohistochemical analysis showed that the expression levels of IL-6, IL-6R, and STAT3 in tumor tissue of mice treated with ginsenoside Rh2 were inhibited." (PMID 39845783, 2024). "The IL-6R expression levels, histology of CRC growth/invasiveness, and tumor growth-related signaling pathway were estimated by H&E and immunohistochemical staining." (PMID 38256960, 2024). "In the anti-IL-6R antibody (tocilizumab; ACTEMRA®, Rhoch Inc., San Francisco, CA, USA) treatment group, the tumor growth was inhibited only in the SW480 xenografts." (PMID 38256960, 2024). "Our computational analysis suggests that HPV − tumor cells have a stronger reliance on IL6/IL6R and CCL2/CCR2 signaling within the tumor microenvironment (TME) to evade NK cell immune attack, in contrast to HPV + tumors." (PMID 38468260, 2024). "IL-6R was weakly corrected with gp130 (r = -0.287, P = 0.006) and JAK2 (r = -0.390, P < 0.001) in tumor tissues, and moderately correlated with gp130 (r = -0.467, P = 0.008) and JAK2 (r = -0.555, P = 0.001) in normal tissues." (PMID 38881895, 2024). "Ginsenoside Rh2 inhibited tumor growth in TNBC mice and reduced the expression of IL- 6, IL-6R, STAT3, Bcl-2, and Bcl-xL in tumor tissues." (PMID 39845783, 2024). "The IL-6 receptor complex, consisting of IL-6Rα/gp80 and gp130, initiates signaling pathways such as Jak/STAT and Erk-1/2, which promote tumor growth and resistance to apoptosis." (PMID 39125732, 2024). "Our data also showed that Fc-VFD combined with Actemra (tocilizumab, anti-IL6R) or Avastin (Bevacizumab, anti-VEGF-A) are successful therapeutic strategies to normalize intratumor vessels and inhibit tumor growth." (PMID 35895109, 2023). "Apart from the PI3K/AKT pathway (CDC37, IL6R), Epidermal-Mesenchymal transition (IL6R, SHC2), tumour metastasis and T1/T2 activation are highlighted (DLL1, STAT4, IL6R)." (PMID 36834486, 2023). "There is a number of clinically registered anti-IL6 and anti-IL6R antibodies that could potentially be exploited in this area; however, caution should be exerted with immune therapies until a better understanding of the biology of these tumours and responses to treatment are known." (PMID 37419892, 2023). "The process of immunosuppression is reflected in that these cytokines can activate IL-6R+ malignant cells and myeloid cells, thereby activating STAT3 signaling and promoting tumor growth." (PMID 35965504, 2022). "At 72 h, colon and tumour tissue were collected and examined for histopathological changes and RT-PCR for genes of interest; TLR4, MD-2, CD-14, MyD88, IL-6, IL-6R, CXCL2, CXCR1, and CXCR2." (PMID 35962138, 2022).
tumor (continued). "Utilizing the humanized IL-6R antibody, tocilizumab, our in vitro and in vivo data show that MSL TNBCs treated with tocilizumab together with chemotherapy results in delayed tumor progression compared to MSL TNBCs treated with docetaxel alone." (PMID 35260569, 2022). "Using an in vitro complementation approach to model inter-clonal tumor cell interactions, we find that IL-6 secreted by HER2neg and IL-6 unresponsive IBC cells drives proliferation of HER2pos and IL-6R-expressing IBC cells." (PMID 35565421, 2022). "In fact several genes such as CKS1B, PSMD4, IL6R, MCL1 involved in proliferation and survival of tumour cells, mechanisms of chemo refractoriness, and alteration of the microenvironment are located in the 1q21 region." (PMID 36755858, 2022). "Functional assays demonstrated that miR-23c acts as tumor suppressor in basal/claudin-low MDA-MB-231 and MDA-MB-468 cells, through the repression of IL-6R." (PMID 35406622, 2022). "Using the xCELLigence plates, we observed that combined therapy against the IL6R/STAT-3 axis and TIGIT increased the cytotoxicity of NK cells against tumor cells." (PMID 35465350, 2022). "High-affinity binding to both tumour targets, EGFR and PD-L1, as well as to IL-6R was observed via biolayer interferometry." (PMID 36439165, 2022). "Studies have reported that the tumor cells with constitutive expression of STAT-3 maintain the activity of this pathway through positive autocrine feedback between IL-6 and the IL6R." (PMID 35465350, 2022). "IL6 secreted by tumor cells interacts with gp130 and interleukin 6 receptor (IL-6R) on ALDEFLUOR-positive mesenchymal cells (MCs) and can promote the homing of MSCs to the tumor sites, as well as stimulate CXCL7 expression by these cells." (PMID 35251985, 2022). "IL-6, gp130 and IL-6Rα were included to one DSS multivariate analysis that also included gender, age and tumor size in one Cox regression survival model." (PMID 32621022, 2021). "In order to test the tumor responsiveness to IL6, the expression of IL6R isoforms and IL6ST were evaluated in all TCGA tumors." (PMID 34576335, 2021). "They concluded with the result that indicated an effective treatment target with a combination of anti-IL-6R and STAT3 inhibitor as this was shown to reduce the tumour progression further." (PMID 34336101, 2021). "Differential analysis of IL6, IL6R, and IL6ST revealed that these genes were significantly modulated in most of the selected TCGA tumor cohorts (n = 33) compared to normal tissues." (PMID 34576335, 2021). "The results outlined that more than 60% of the total mirDIP-predicted miRNAs were significantly correlated (Pearson’s correlation value ≥ 0.3 or ≤ −0.3; p ≤ 0.05) with the expression of each gene in at least one tumor type (IL6: 67%, IL6R: 70% and IL6ST: 64%)." (PMID 34576335, 2021). "In the tumor model BoC32, we observed in SR tumors an upregulation of IL-6 family members such as Ciliary Neurotrophic Factor Receptor (CNTFR) and Interleukin 6 receptor (IL6R), known to be able to signal via Janus kinase (JAK)/(STAT)." (PMID 34271981, 2021). "Interestingly, IL-6R neutralization negatively regulates angiogenesis and tumor growth through IL-6 signaling downregulation, supporting the hypothesis that considers IL-6 signaling proteins to be useful targets in CRC therapy and in several other human diseases." (PMID 33923292, 2021). "IF demonstrated IL6R protein in myofibers in all conditions (top) as well as robust staining of muscle blood vessels in the KPC tumor mice (bottom)." (PMID 33851955, 2021). "Our bioinformatic analysis revealed that IL6, IL6R, and IL6ST genes were significantly modulated in most of the cancers showing a tumor-dependent pattern." (PMID 34576335, 2021). "So far, most reports about the mechanism that the tocilizumab inhibits the tumor growth are dependent on blocking IL6 and IL6R signaling." (PMID 33576874, 2021).